SPAST (spastin)
Diseases named in the same sentence as SPAST in open-access papers (continued):
Sharing a sentence is not in itself a finding about the gene and the disease.
hereditary spastic paraplegia (continued). "Variants in proteins involved in microtubule dynamics (SPAST), axonal maintenance (ATL1) and transport (KIF1A) are among the most common genetic etiologies both of cerebral palsy mimicries and of hereditary spastic paraplegia (HSP)." (PMID 40095113, 2025). "The presented study indicates that microrearrangements in SPAST lead to hereditary spastic paraplegia not only via haploinsufficiency." (PMID 38732227, 2024). "Spastin gene mutations are also thought to be one of the primary causes of a series of heterogeneous neurodegenerative disorders known as hereditary spastic paraplegia (HSP)." (PMID 36090256, 2022). "Mutations in ER-shaping proteins such as Spastin, ATL1, RTN2 or REEP1 that couple the tubular ER network with microtubule dynamics cause hereditary spastic paraplegia." (PMID 35650592, 2022). "Spastic paraplegia 4 (SPG4), the most common autosomal dominant form of hereditary spastic paraplegias (HSP), is caused by loss of function mutations in the SPAST gene that encodes spastin, a member of microtubule severing protein." (PMID 36414997, 2022). "Mutations in both SPAST and NIPA1 have been identified as causes of hereditary spastic paraplegia, a condition which causes progressive weakness and spasticity of the legs." (PMID 33562221, 2021). "Spastic paraplegia type 4 (SPG4) is caused by mutations in the SPAST gene, is the most common form of autosomal-dominant pure hereditary spastic paraplegias (HSP), and is rarely associated with a complicated form that includes ataxia, epilepsy, and cognitive decline." (PMID 34753439, 2021). "Mutations in SPG7 and SPAST are common causes of hereditary spastic paraplegia (HSP)." (PMID 32973427, 2020). "Our results reveal a dual role of spastin to shape ER tubules and to regulate LD movement along microtubules, opening new perspectives for the pathogenesis of hereditary spastic paraplegia." (PMID 32321733, 2020). "Interestingly, mutation of human spastin is the most frequent cause of hereditary spastic paraplegias (HSP; Solowska & Baas, 2015), while mammalian katanin has been associated with behavioral deficits and intellectual disability." (PMID 31702858, 2020). "The coordination of lipid droplet dispersion and reticulum shaping under the control of Spastin is a unique trafficking model, affected in the different forms of hereditary spastic paraplegia." (PMID 32315314, 2020). "Here we show that Spastin, one of the major proteins involved in Hereditary Spastic Paraplegia (HSP), controls LD dispersion." (PMID 32315314, 2020). "This study identifies deficits in working and associative memory in spastin knockout mice, resembling the cognitive deficits described in humans with severe forms of SPG4-type hereditary spastic paraplegia." (PMID 32866173, 2020). "The balance between HIPK2-mediated phosphorylation and neddylation-dependent degradation controls spastin protein levels, revealing novel therapeutic targets for hereditary spastic paraplegia." (PMID 33106322, 2020). "Hereditary spastic paraplegia (HSP) is a genetically heterogeneous disease caused by mutations in many genes, including those encoding spastin, strumpellin, or REEP1." (PMID 28389476, 2017). "To overcome these limitations, we performed a comprehensive neuroimaging study in a large cohort of patients with molecular confirmation of SPG4/Spastin-related hereditary spastic paraplegia." (PMID 25658484, 2015). "Indeed, these MT severers are involved in human cortical malformations for p60-katanin and hereditary spastic paraplegia for spastin." (PMID 39613968, 2025). "Restoring spastin protein levels could be beneficial for patients with hereditary spastic paraplegia." (PMID 38551087, 2024). "Since pathogenic mutations in the SPG4 gene encoding Spastin lead to the development of hereditary spastic paraplegia (HSP), earlier investigations on Spastin function have mostly focused on functions of M1 isoform which is thought to be responsible for HSP in neuronal cells." (PMID 36766769, 2023).
hereditary spastic paraplegia (continued). "Spastin was originally found in the context of hereditary spastic paraplegia (HSP)." (PMID 35865632, 2022). "ATL1, RTN2, SPAST and REEP1 are the causative genes of hereditary spastic paraplegia (HSP)." (PMID 29310658, 2018). "Deletions in SPAST gene are common in hereditary spastic paraplegia." (PMID 30373198, 2018). "Defects in axonal transport have also been reported in mouse models of spastin-mediated hereditary spastic paraplegia (SPG4), and swellings containing vesicular and cytoskeletal proteins, including neurofilament proteins, have been reported in humans with this disease." (PMID 21087519, 2010). "However, several other proteins such as Ndel1, the partner of LIS1 involved in lissencephaly, ASPM involved in microcephaly, or spastin involved in hereditary spastic paraplegia, are also neuronal MAPs." (PMID 18782428, 2008). "A reduction in spastin protein levels is responsible for approximately 40% of cases of Hereditary Spastic Paraplegia (HSP), a neurodegenerative disease." (PMID 39920118, 2025). "The most widely represented hereditary spastic paraplegia (HSP) was autosomal dominant spastic paraplegia type 4 (SPG4), which is associated with mutations in the SPAST gene (n = 8)." (PMID 40883749, 2025). "The most common form of hereditary spastic paraplegia (HSP), SPG4 is caused by single nucleotide variants and microrearrangements in the SPAST gene." (PMID 38732227, 2024). "Defective ER shaping mediated through proteins stabilizing the tubule (Atlastin, Spastin) or sheet (CLIMP 63, p180, KTN) conformation have been associated with the inherited neurologic disorder, hereditary spastic paraplegia (HSP)." (PMID 39337270, 2024). "Mutations in spastin, strumpellin, or REEP1 cause hereditary spastic paraplegia (HSP), a disease characterized by axonal degeneration." (PMID 28389476, 2017). "Mutations in the SPG4 gene (spastin) and in the SPG3A gene (atlastin) account for the majority of 'pure' autosomal dominant form of hereditary spastic paraplegia (HSP)." (PMID 18644145, 2008). "Finally, it is worth mentioning that mutations inthe spastin, strumpellin, or REEP1 genes cause hereditary spastic paraplegia (HSP)." (PMID 37366507, 2022). "We conclude with a brief discussion of the SPG4/SPAST gene and the role of multigene panels in the diagnosis and management of hereditary spastic paraplegia." (PMID 32908740, 2020). "Here we report a novel epistatic interaction between SPAST and the contiguous gene DPY30, which modifies age at onset in hereditary spastic paraplegia, a genetic axonopathy." (PMID 29481671, 2018). "The obtained data indicate that nonsense-mediated decay degradation is not the only mechanism of hereditary spastic paraplegia in patients with SPAST microrearrangements." (PMID 38732227, 2024). "The truncated spastin may damage the corticospinal tracts through an isoform‐specific pathological effect, thereby contributing to the pathogenesis of hereditary spastic paraplegia (HSP). © 2021 The Authors." (PMID 34927746, 2022). "In patient-derived fibroblasts we quantified 124 morphological features in 100,000 cells from 15 people with two genotypes (SPAST and SPG7) of Hereditary Spastic Paraplegia (HSP) and matched controls." (PMID 34404843, 2021).
Spastic paraplegia (35 papers, 2008 to 2025). Complete loss of the ability to move the lower limbs accompanied by spasticity of the lower limbs. "SPAST variants are associated with a wide range of clinical presentations, from the classical pure form of spastic paraplegia to more complex, severe phenotypes." (PMID 40870017, 2025). "She and one of her daughters (II-1) both had a pathogenic SPAST p.Gly382Cys variants which are compatible with their clinical features of spastic paraplegia." (PMID 35778421, 2022). "Spastic paraplegia (SPG) type 4 is an autosomal dominant SPG caused by functional variants in the SPAST gene." (PMID 34035234, 2021). "Next-generation sequencing showed no pathogenic or likely pathogenic mutations in other causative genes of spastic paraplegia such as SPAST and so on." (PMID 32655478, 2020). "This study presents a family with spastic paraplegia due to a novel mutation c.1390G›T(p.Glu464Term) in SPAST gene." (PMID 31837705, 2019). "We also found a new SPAST missense variant (p.Ile328Leu) in a 15 years old male with complicated spastic paraplegia starting at the age of 18 months." (PMID 20932283, 2010). "In a large cohort of Spanish patients with spastic paraplegia, SPAST and ATL1 mutations were found in 15% of the cases." (PMID 20932283, 2010). "Finally, SPAST promotes microtubule growth in the cytoskeleton, playing an important role in neuronal development, and has been implicated in spastic paraplegia with dysarthric speech." (PMID 36117209, 2023). "Finally, a CHMP3 mutation, T173I, located within the MIM used in our binding studies, is associated with spastic paraplegia, a disease associated with SPASTIN defects." (PMID 36107470, 2022). "De novo variants in SPAST are evidenced to be associated with ASD with comorbid spastic paraplegia." (PMID 33562221, 2021). "Mutations in TF binding sites in the SPAST promoter could occur in either familial HSP or in sporadic spastic paraplegia cases." (PMID 22574173, 2012). "Multiple CNVs affecting SPG7 (n = 4), CACNA1A (n = 3), SGCE (n = 3), NKX2-1 (n = 2) and SPAST (n = 2) were detected in individuals with episodic ataxia, dystonia, or spastic paraplegia, respectively." (PMID 36781956, 2023). "In conclusion, we reported the mutational spectrum of the SPAST and ATL1 genes in a large cohort of Spanish patients with spastic paraplegia." (PMID 20932283, 2010). "Interestingly, mutations in kinesin-1 (KIF5A) also cause a spastic paraplegia (MIM 604187), as do mutations in the gene encoding the microtubule-severing protein spastin (SPAST) (MIM 182601), consistent with the proposed mechanism of action for protrudin by Raiborg and colleagues." (PMID 31413155, 2019). "This demonstrates a rapid, non-invasive, and inexpensive test for recognizing the SPG4 hereditary spastic paraplegia subtype and evaluating the effects of spastin-enhancing drugs in non-neuronal cells." (PMID 40076577, 2025). "The different genetic forms are assigned spastic paraplegia loci (SPG), although the HSP genes may also be listed according to the new MDSGene nomenclature, e.g. SPAST-HSP for SPG4." (PMID 33646413, 2021). "A novel MIT domain mutation was also identified in a patient attending the East Anglian Medical Genetics Service, with a phenotype consistent with pure HSP and no family history of spastic paraplegia, R115C (SPAST c.343C>T)." (PMID 31787869, 2019). "However, we assume that haploinsufficiency is not the only mechanism contributing to hereditary spastic paraplegia by microrearrangements in the SPAST gene." (PMID 38732227, 2024).
Cognitive impairment (13 papers, 2010 to 2025). Abnormal cognition is characterized by deficits in thinking, reasoning, or remembering. "A novel heterozygous mutation in the SPAST gene in a Chinese family was linked to cognitive impairment and spastic paraparesis." (PMID 32536902, 2020). "In summary, the present study provides the first evidence that the loss of spastin resembles cognitive deficits of patients with SPG4-type HSP and suggests that they depend on synaptic changes in the CNS." (PMID 32866173, 2020). "Neurologic co-symptoms associated with patients with SPAST mutations were mainly bladder disturbances, cognitive impairment and depression, being discussed in detail elsewhere." (PMID 20214791, 2010). "Furthermore, 8 patients with pathogenic SPAST mutations had pHSP and 4 were diagnosed with cHSP and exhibited different degrees of cognitive impairment (33%)." (PMID 20214791, 2010). "Using heterozygous and homozygous spastin knockout mice, we confirmed the previously known deficits in motor performance and for the first time observed cognitive impairments that show some similarity with cHSP phenotypes." (PMID 32866173, 2020). "The observed deficits in synaptic cargo delivery and synaptic transmission are in agreement with cognitive deficits in spastin knockout mice and patients with cHSP." (PMID 32866173, 2020).
Ataxia (11 papers, 2015 to 2025). Ataxia refers to impaired coordination of voluntary muscle movement. "SNX14 deficiency disrupted microtubule organization and mitochondrial transport in axons by destabilizing the microtubule-severing enzyme spastin, which is implicated in dominant hereditary spastic paraplegia with cerebellar ataxia, and compromised axonal integrity and mitochondrial function." (PMID 34691693, 2021). "Interestingly, mutations in the ATL1, SPAST, RAB7A or KATNB1 genes have been previously associated with diseases presenting with hyperreflexia, sensory axonal neuropathy or sensory impairment among other signs, which overlap with clinical signs identified in this new ataxia subtype in our family." (PMID 35310830, 2022). "Our study revealed an unprecedented role for SNX14-dependent axonal transport in cerebellar ataxia, demonstrated the convergence of SNX14 and spastin in mitochondrial dysfunction, and suggested valproate as a potential therapeutic agent." (PMID 34691693, 2021).
dementia (8 papers, 2016 to 2026). Loss of intellectual abilities interfering with an individual's social and occupational functions. "Although this conclusion is based on correlation, human patients with SPG4 (spastin encoding gene) develop intellectual disabilities and late-onset dementia." (PMID 32866173, 2020). "In patients with dementia that presented with a deletion of exon 17 of the SPAST gene, the neuropathological examination showed widespread ubiquitin positivity within the neocortex and white matter and rare tau-positive lesions in the frontal, temporal regions." (PMID 27688599, 2016).
autosomal dominant spastic paraplegia 4 (7 papers, 2018 to 2026). "Autosomal dominant spastic paraplegia-4 (SPG4) with relatively pure lower limb spastic paraplegia is caused by heterozygous mutations in the SPAST gene." (PMID 29875629, 2018). "Furthermore, variants in SPAST are generally known to cause autosomal dominant spastic paraplegia 4 in humans, which is also increasingly associated with additional neurological symptoms such as epilepsy." (PMID 36899667, 2023). "Another example is SPAST, an established gene for autosomal dominant spastic paraplegia 4 (MIM: 182601)." (PMID 33456446, 2020). "Autosomal dominant spastic paraplegia type 4 (SPG4, SPAST gene) is commonly described as a pure phenotype with progressive spastic weakness of the lower limbs." (PMID 41180955, 2025).
Alzheimer disease (6 papers, 2015 to 2022). A progressive, neurodegenerative disease characterized by loss of function and death of nerve cells in several areas of the brain leading to loss of cognitive function such as memory and language. "Finally, the possibility to pharmacologically modulate spastin levels opens the way to potential clinical implications also in promoting axon regeneration after nerve injury and in neurodegenerative diseases associated to spastin dysfunctions, such as Alzheimer’s disease." (PMID 33106322, 2020). "Thus, spastin is the effector of microtubule breakdown in this cell culture model of Alzheimer disease." (PMID 26691836, 2015).
hereditary spastic paraplegia type 4 (6 papers, 2018 to 2025). "Hereditary spastic paraplegia type 4 (SPG4), which is autosomal dominant, is the clinical subtype associated with SPAST mutations." (PMID 38882014, 2024). "Other genomic diagnoses not included in the clinical outcome audit, include DNAL1 (Primary ciliary dyskinesia 16, MIM: 614017), SPAST (Spastic paraplegia 4, MIM:182601) and FGFR3 (Thanatophoric dysplasia, MIM:187600)." (PMID 38577897, 2024). "The non-standard decision made by the Senior Underwriter and Chief Medical Officer for a 33 year old female positive for SPAST for SPG4 (hereditary spastic paraplegia type 4) was to decline death, trauma and TPD cover." (PMID 29891881, 2018).
paraplegia (6 papers, 2014 to 2025). Complete paralysis of the lower half of the body including both legs, often caused by damage to the spinal cord. "Spastin gene mutations cause spastic paraplegia 4 (SPG4) subtype, which represent about 40% of AD-HSP6." (PMID 28603788, 2016). "Forty percent of the dominantly inherited paraplegias with a pure HSP phenotype are due to mutations in Spastic Gait 4 [SPG4, alternative Gene name Spastic Gait 4 (SPAST)] encoding spastin." (PMID 24381312, 2014). "Furthermore, anti-hnRNP A1-M9 antibodies transfected into human neuronal cells in vitro altered RNA levels of the spastic paraplegia genes (SPGs) spastin (SPG4), spartin (SPG20), and paraplegin (SPG7) as shown by microarray." (PMID 27375925, 2016).
Spastic paraparesis (6 papers, 2014 to 2025). Partial loss of the ability to move the lower limbs accompanied by spasticity of the lower limbs. "The phenotype in our family, adult-onset, pure spastic paraparesis with slow progression, is concordant with other truncating SPAST variants, reinforcing the strong correlation between loss-of-function variants and pure HSP forms." (PMID 41149788, 2025). "Among the 47 cases carrying SPAST mutations, 44 (94%) showed spastic paraparesis and 3 (6%) were asymptomatic." (PMID 25421405, 2014).
motor neuron disease (5 papers, 2011 to 2024). "Interaction of ZFYVE27 with spastin, VAP-A/B and KIF5A highlights its role in motor neuron disease." (PMID 22216323, 2011).
epilepsy (4 papers, 2021 to 2025). A brain disorder characterized by episodes of abnormally increased neuronal discharge resulting in transient episodes of sensory or motor neurological dysfunction, or psychic dysfunction. "While little is known about the potential roles of CCDC85A and SPAST in epilepsy pathogenesis and few functional studies have been conducted, they remain interesting candidate genes." (PMID 36899667, 2023). "As for SPAST, there is some evidence that it might have a role in the pathogenesis of epilepsy (PS3)." (PMID 36899667, 2023). "However, the current knowledge on spastin’s role in epilepsy pathogenesis is insufficient to fulfill ACMG’s PS3 criterion." (PMID 36899667, 2023). "As with CCDC85A, little is known about SPAST’s role in epilepsy pathogenesis, and the PS3 criterion is not fulfilled." (PMID 36899667, 2023).
amyotrophic lateral sclerosis (3 papers, 2011 to 2022). Amyotrophic lateral sclerosis (ALS) is a neurodegenerative disease characterized by progressive muscular paralysis reflecting degeneration of motor neurons in the primary motor cortex, corticospinal tracts, brainstem and spinal cord. "Mutations in spastin and KIF5A are the primary cause for HSP and mutation in VAP-B causes amyotrophic lateral sclerosis (ALS)." (PMID 22216323, 2011).
autism (3 papers, 2017 to 2025). Persistent deficits in social interaction and communication and interaction as well as a markedly restricted repertoire of activity and interest as well as repetitive patterns of behavior. "Of note, the previously under-recognised association with autism and psychiatric illness needs to be confirmed in other cohorts and genes to determine if this is a specific effect of SPAST mutations." (PMID 28572275, 2017). "Their spatial proximity, combined with the structural and functional importance of this domain, may raise the hypothesis of an “autism hotspot” within SPAST, where specific variants preferentially impact early cortical wiring and synaptic maturation." (PMID 40870017, 2025).